MIR200A (microRNA 200a)
Synonyms: hsa-mir-200a; MIRN200A; mir-200a
Gene: MicroRNA gene on chromosome 1 (1,167,863 to 1,167,952, forward strand). Ensembl gene ENSG00000207607.
Gene Ontology:
Biological process: miRNA-mediated post-transcriptional gene silencing
Cellular component: RISC complex
Homologues: Orthologues: chimpanzee ptr-mir-200a (100% identical), macaque mml-mir-200a (99% identical), guinea pig MIR200A (92% identical), mouse Mir200a (92% identical), tropical clawed frog xtr-mir-200a (69% identical), zebrafish mir200a (66% identical), dog MIR200A (63% identical), zebrafish mir141 (63% identical), Drosophila melanogaster mir-8 (57% identical), rat Mir3548 (57% identical). Paralogues in human: MIR200B (60% identical), MIR200C (42% identical).
Diseases named in the same sentence as MIR200A in open-access papers:
MIR200A is named in the same sentence as 6 diseases in open-access papers, as found by Europe PMC text mining. Sharing a sentence is not in itself a finding about the gene and the disease. The quoted sentences say what the papers report.
glioma (1 paper, 2020). A benign or malignant brain and spinal cord tumor that arises from glial cells (astrocytes, oligodendrocytes, ependymal cells). "The cancer genes MIR200A, MIR200B, and MIR429 in the different aberrant chromosomal region 1p36.33-p36.32 between tumor tissue (no aberration) and cell subpopulations (gain) have been described as implicated in regulation of tumor cell proliferation in glioma." (PMID 32634135, 2020).
lymphoid tumor (1 paper, 2022). "A total of six miRNA orthologs – MIR21, MIR30E, MIR106B, MIR10B, MIR200A, and MIR200B were identified as differentially expressed orthologs among mammary tumor cell lines, lymphoid tumor cell lines, and normal epithelial cell cultures (importance ≥10 and p≤0.01) (Figure-2)." (PMID 35765483, 2022).
cancer (2 papers, 2020). A tumor composed of atypical neoplastic, often pleomorphic cells that invade other tissues. "GRHL2 upregulates expression of the MIR141, MIR200A, MIR200B, MIR200C and MIR429 microRNAs by binding to their regulatory elements in a number of cancers." (PMID 32005677, 2020).
MIR200A also shares sentences with these, for which no sentence is quoted: tumor (2 papers); mammary tumor (1); pancreatic cancer (1).